ERG (ETS transcription factor ERG)
Diseases named in the same sentence as ERG in open-access papers (continued):
Sharing a sentence is not in itself a finding about the gene and the disease.
prostate carcinoma (continued). "We analyzed 110 primary prostate cancer samples, 70 metastatic tumor samples from 11 patients, and 27 xenograft tissues derived from 22 advanced prostate cancer patients using fluorescence in situ hybridization (FISH) analysis with probes targeting the TMPRSS2/ERG, PTEN, and AR gene loci." (PMID 24098661, 2013). "Additionally, increased MTC02 expression is a strong predictor of poor clinical outcome in ERG negative cancers, highlighting a potentially important role of elevated mitochondrial content for prostate cancer cell biology." (PMID 24261794, 2013). "We selected independent tissues (not used for expression analysis) from the Innsbruck prostate cancer biobank in order to further ensure that our investigation would reveal general ERG+ prostate cancer-related alterations rather than patient-specific differences." (PMID 23390522, 2013). "This striking difference may be caused by the substantial increase of cellular mitochondrial content by ERG rearrangements, which by themselves do not have any prognostic impact on prostate cancers." (PMID 24261794, 2013). "We divided all prostate cancer samples of the studies included in the meta-analysis into three groups, based on their ERG expression level: ERG overexpression-positive samples, ERG intermediate samples, and ERG overexpression-negative samples." (PMID 23390522, 2013). "Here we examine the accuracy of exoRNA to predict tissue expression of the prostate cancer-related gene fusion TMPRSS2:ERG (T:E) as well as determine the ability of biomarkers to differentiate prostate cancer-positive (BxPos) from prostate cancer-negative (BxNeg) patients." (PMID 26082317, 2013). "In addition, although ERGIC1 and TMED3 were highly expressed in both ERG negative and positive prostate cancers, their mRNA expression levels positively correlated with ERG expression levels in ERG positive samples (P = 0.002 and P = 0.007 respectively)." (PMID 22761906, 2012). "However, the biological role of ETS fusions in prostate cancer development is still controversial, since ERG and ETV1 by themselves, do not seem to be tumorigenic." (PMID 21829708, 2011). "In addition to the e4-e2 TIC isoform, which was observed specifically in ERG-negative prostate cancer samples, another isoform e1-e2 has been observed in both prostate cancer and benign prostate tissue, and found to be regulated by androgen levels." (PMID 21261984, 2011). "ERG was shown to induce the expression of PLA2G7, and knock-down of PLA2G7 significantly reduced the growth of ERG positive, but not ERG negative, prostate cancer cells in vitro, indicating potential as a biomarker and personalized drug target in ERG positive prostate cancers." (PMID 22202492, 2011). "This suggested that ERG and ESE3 could affect transcription of many genes in opposite directions and that ERG up-regulation and ESE3 down-regulation could results in partially similar effects on the prostate cancer transcriptome." (PMID 20479932, 2010). "However, two cohort studies of men with clinically localised prostate cancer who did not undergo treatment (i.e. watchful waiting) showed that men who had TMPRSS2:ERG fusion had lower prostate cancer-specific survival compared to men without fusion expression." (PMID 17971772, 2007). "In this study, we accordingly utilized Hematoxylin and Eosin (H&E)-stained whole slide images (WSIs) of prostate adenocarcinoma and sought to develop a deep learning algorithm that could distinguish ERG rearranged prostate cancers from those without ERG rearrangement." (PMID 35513774, 2022). "Furthermore, treatments with inhibitors of ERRα (XCT790) and ERG (EIP1) could reduce the protein levels of eNOS in VCaP cells, suggesting that both ERRα and ERG could act as the upstream regulators of eNOS in prostate cancer cells and PCSCs." (PMID 35526071, 2022).
prostate carcinoma (continued). "However, when FGF2 antagonists were used to block the interactions between endothelial cells and prostate cancer cells, the expression of ERG could not be completely reversed." (PMID 33425737, 2020). "SFRP4 may well become an element of such a test for ERG negative prostate cancer." (PMID 32677026, 2020). "For example, in a subgroup of patients with castrate resistant prostate cancer, tumors with ERG-rearrangement but no detectable ERG protein expression may indicate a non-functional AR pathway, suggesting that these patients may not benefit from therapy directed against the AR pathway." (PMID 31741711, 2019). "However, BCAR1 may be a useful marker if combined with other molecular markers, especially for ERG-negative prostate cancer." (PMID 29304771, 2018). "Thus the BCAR1 biomarker may best aid in decision making if combined with other marker in ERG-negative prostate cancer." (PMID 29304771, 2018). "Thus, the expression of TRIM25 in prostate cancer cells may not result in reduced ERG protein levels when USP9X is also expressed." (PMID 27626314, 2016). "Also, the impact of MCT2 inhibition in PCa cells is still unknown and links between SLC16A7/MCT2 and major prostate cancer drivers such as Androgen Receptor (AR) ETS-related genes (ERG) have not previously been studied." (PMID 26035357, 2015). "Therefore, RAS/ERK activation does not drive oncogenic ETS expression in prostate cancer cell lines, however in at least one context (ERG in RWPE) an oncogenic ETS could induce the phosphorylation of both AKT and, to a lesser degree, ERK." (PMID 24642271, 2014). "In this study, we hypothesize that multiple TMPRSS2:ERG fusion subtypes and additional low-prevalent TMPRSS2:ETS fusion genes are collectively more informative than any single marker alone in the noninvasive detection and stratification of clinically significant prostate cancer." (PMID 24133629, 2013). "However, the origin of prostate cancer from basal cells was recently suggested by Witte and coworkers who reported that basal cells isolated from primary benign human prostate tissue and transfected with AR and AKT/ERG were able to establish prostate tumors in NSG mice." (PMID 23358633, 2013). "It is also demonstrated that co-activation of the PI3K/AKT pathway and ERG overexpression collaborate with a lack of PTEN and prostate-specific androgen response in the development of prostate carcinoma." (PMID 39940843, 2025). "AQP5 positivity was observed in ERG-positive (15.5%), ERG-negative (5.8%), with PTEN deletion (14.7%) and without PTEN deletion (9.4%) prostate cancers." (PMID 36672280, 2023). "Prostate cancers can be broadly classified into those with rearrangements in ETS family transcription factors (i.e., ERG, ETV1, ETV4, and FLI1) and those without." (PMID 35050902, 2022). "In situ ERG protein expression is an independent predictor of BCR and CR in prostate cancer patients with undetectable PSA and who did not receive adjuvant treatment after surgery." (PMID 35574900, 2022). "In earlier studies using the same prostate cancer TMA, several molecular parameters had been identified that were only prognostic in either ERG positive or ERG negative cancers." (PMID 32488048, 2020). "The availability of a molecular database attached to this prostate cancer TMA enabled us to investigate the role of SNW1 in molecularly defined cancer subgroups, the most relevant of which are ERG positive and ERG negative cancers." (PMID 31043167, 2019).
prostate carcinoma (continued). "Strikingly none of the NEPC tumors with TNC amplification was independent of the alterations of the master genes ERG and MYC, indicating a selective co-segregation of TNC along with MYC and ERG amplification in the subtype of aggressive prostate cancers." (PMID 31798767, 2019). "Here, we used human prostate cancer samples and showed that the vast majority of human SPOP-mutant cancers do not express ERG." (PMID 29202479, 2018). "Therefore, the observed prostate cancer genomic and expression alterations of different genes may affect the same pathway resulting in comparable expression profiles between ERG-positive and ERG-negative prostate tumor types." (PMID 30150711, 2018). "Transcriptome analysis of VDR signaling in prostate cancer cells has been limited to microarray analysis and has not included a TMPRSS2:ERG positive cell line." (PMID 28591703, 2017). "Fusion of this gene to members of the ETS family of transcription factors, in particular ERG or ETV1, leads to overexpression of the oncogenes in a large portion of prostate cancer cases, but not in benign prostate samples, in an androgen-dependent manner." (PMID 27285981, 2016). "Tudor domain-containing protein 1 gene (TDRD1) was reported to be differentially expressed between TMPRSS2:ERG-negative and TMPRSS2:ERG-positive prostate cancer." (PMID 23555854, 2013). "Our previous expression profiling study of human prostate cancer specimens revealed that TDRD1 is, apart from ERG, the most differentially expressed gene between TMPRSS2:ERG-negative and -positive tumors." (PMID 23555854, 2013). "To explain the observed co-expression, we employed cellular models of prostate cancer, including cells representing benign (RWPE-1, BPH-1), fusion-negative (PC-3, DU145), ERG-rearranged (VCaP, NCI-H660) and ETV1-rearranged (LNCaP) prostate cancer." (PMID 23555854, 2013). "At the genomic level, studies using large clinical cohorts demonstrated both presence and absence of enrichment between TMPRSS2:ERG fusion and PTEN gene deletion in prostate cancer." (PMID 24098661, 2013). "SPINK1 is emerging as a biomarker of a molecular subtype of prostate cancer, in the absence of gene rearrangements/fusions such as TMPRSS2:ERG." (PMID 22641253, 2012). "Similar analysis on GEDI-captured CTCs from a CRPC patient revealed the presence of both ERG positive and ERG negative cells, while CD45+ leucocytes were negative for ERG protein, indicating the specificity of ERG staining for prostate cancer-derived cells." (PMID 22558290, 2012). "In prostate cancer, only the linear kernel performed well (median ARI of 0.54) with the correct number of clusters (2 for ERG fusion or no fusion), but ANF and IntNMF also achieved decent performance with median ARIs of 0.39 and 0.33 respectively when three clusters were considered." (PMID 39102448, 2024). "Additionally, it has been reported that epigenetic events affected by genetic variation differentially regulate miRs in African American prostate cancer patients and are drivers of TMPRSS2:ERG-negative tumors." (PMID 33243086, 2020). "Fusion of this gene to members of the ETS family of transcription factors, in particular oncogenes ERG or ETV1, leads to over-expression of these transforming agents in a significant portion of prostate cancers, but not benign prostate tissue, in an androgen-dependent manner." (PMID 29455671, 2018). "TMPRSS2:ERG is growth promoting in VCaP prostate cancer cells and in mouse models, although whether androgen or 1,25D(OH)2D3 induction of the already highly expressed TMPRSS2:ERG increases ERG activity had not been examined." (PMID 28591703, 2017). "The downstream targets of ERG and ETV1 in prostate cancer have not yet been identified." (PMID 27285981, 2016).
prostate carcinoma (continued). "Interestingly, ERG is not expressed in PC3 cells, suggesting that miR-205 expression in prostate cancer cell line can be ERG-independent." (PMID 27191272, 2016). "Finally, miR-200b subfamily members and miR-205 are not induced by ERG in murine prostate derived from the pbsn-ERG transgenic mice, suggesting that ERG transgenic mice do not fully mimic the TMRPSS2/ERG-dependent prostate cancer development in human." (PMID 27191272, 2016). "The impact of such SRs for prostate cancer biology is currently not understood, but a reasonable hypothesis is that they develop – like the TMPRSS2:ERG gene fusion – as a consequence of highly active androgen receptor (AR) signaling." (PMID 24684958, 2014). "Using a genome-wide interrogation strategy to identify genes that are expressed abundantly in human prostate cancer but sparsely in non-cancerous adult tissues, we previously identified numerous putative prostate TAAs including ETS related gene (ERG) and Single-minded homolog 2 (SIM2)." (PMID 24690990, 2014). "No information exists regarding NDRG1 protein expression in prostate cancer; whether found to be fused to ERG or not, NDRG1 could be a useful protein biomarker for prostate cancer." (PMID 24386364, 2013). "Among genes deregulated in ERG-rearranged prostate cancer, at least two independent studies identified Tudor domain-containing protein 1 (TDRD1) as the most differentially expressed gene between ERG rearrangement-positive and -negative prostate cancer, apart from ERG itself." (PMID 23555854, 2013). "The TMPRSS2:ERG fusion gene is not present in non-neoplastic prostate epithelium, but has been described in high-grade prostatic intraepithelial neoplasia (HGPIN) lesions, suggesting that it might represent an early event in the development of prostate cancer." (PMID 33634124, 2021). "In addition, the seven articles supporting the connection between ERG and SP1 are from 2007 and earlier, suggesting that the previous studies of Ewing’s sarcoma and acute myeloid leukaemia, and not prostate cancer, may have been overlooked." (PMID 29342271, 2018). "Thus, a CYP24A1 resistant VDR agonist may be beneficial for treatment of TMPRSS2:ERG positive prostate cancer; one negative consequence of TMPRSS2:ERG expression is inactivation of VDR signaling." (PMID 28591703, 2017). "In addition, in vitro studies, SOX9 expression is suppressed by androgens in ERG-negative prostate cancer cells, therefore ADT may actually induce SOX9 expression in ERG-negative patients." (PMID 27863438, 2016).
prostate tumors (128 papers, 2008 to 2025). "In contrast, CHD1 deletion is mutually exclusive with PTEN loss or TMPRSS2:ERG fusion in human prostate tumors, by crosstalk with key components in PTEN-AKT and AR signaling pathways." (PMID 36776288, 2023). "Wild-type ERG cannot promote tumor formation alone, but ERG can promote prostate tumor formation in cooperation with mutations that activate the PI3K/AKT pathway." (PMID 34314419, 2021). "In this study we found that activation of AKT changes the genes that ERG regulates, leading to luminal epithelial differentiation, which is a hallmark of most prostate tumors." (PMID 34314419, 2021). "We also demonstrated that the 3′ splice site SSO caused a reduction in ERG expression in a patient-derived prostate tumour tissue cultured ex vivo." (PMID 32581342, 2020). "The most common genomic alteration identified in prostate tumors is the fusion of the 5′ untranslated region of TMPRSS2 with ERG caused by deletions or translocations, which is found in 40–50% of samples." (PMID 28750683, 2017). "In the ERG positive group, single ERG alteration was strongly associated with GS = 6 prostate tumors." (PMID 29088771, 2017). "Collectively, these results establish that TRIM25 is an ubiquitin ligase of full-length ERG as well as the N-terminally truncated ERG variants that originate from the TMPRSS2-ERG gene fusion in prostate tumors." (PMID 27626314, 2016). "Further supporting this model, we have shown that these rare activating mutations in RAS or RAF are mutually exclusive with ERG gene rearrangements in prostate tumors." (PMID 25885538, 2015). "Studies have reported a higher frequency of PTEN loss and TMPRSS2:ERG fusion in prostate tumours of Black/African American men, which may contribute to the more aggressive nature of the disease in this population." (PMID 40165885, 2025). "However, primary prostate tumors have relatively few mutations, and only three genes (ERG,PTEN, andSPOP) are recurrently mutated in more than 10% of primary tumors." (PMID 30135717, 2018). "Furthermore, 17 and 25 of the ERG positive prostate tumors, respectively, harbored SLC45A3 or PTEN expression loss." (PMID 29088771, 2017). "Based on these results, we hypothesized that a decrease in ERF expression in prostate tumor samples can cause activation of the ETS transcriptional program similar to ERG activation." (PMID 28750683, 2017). "Interestingly, these data implicated also that ESE3 loss had consequences quite similar to ERG over-expression on the transcriptional program of prostate tumors." (PMID 20479932, 2010). "Because of this characteristic, the expression of the TMPRSS2:ERG fusion gene leads to the overexpression of the ERG transcription factor in the presence of androgens in about 50% of prostate tumors." (PMID 40332527, 2025). "The test measures the expression levels of three exosomal RNA biomarkers—ERG (ETS-related gene), PCA3 (prostate cancer antigen 3), and SPDEF (SAM pointed domain-containing ETS transcription factor)—which are associated with prostate tumor formation." (PMID 41374944, 2025). "In fact, gene rearrangement is observed in the majority (57–80%) of PCa tissue samples, and the TMPRSS2/ERG rearrangement in particular is present in 50% of prostate tumors." (PMID 38674385, 2024). "Because the expression of ERG in prostate tumor tissue is primarily driven by the TMPRSS2–ERG fusion event, we inferred the ERG fusion status based on the expression level of the ERG gene." (PMID 39347576, 2024). "Primary prostate tumors with ERG gene rearrangement have increased FASN expression and we find evidence of FASN hypomethylation in this context." (PMID 38112617, 2024). "Using whole exome sequencing, FISH, or confocal microscopy, several groups showed the mutual exclusivity of CHD1 deletion with ERG fusion in human prostate tumors." (PMID 36776288, 2023).